CD47 (CD47 molecule)
Diseases named in the same sentence as CD47 in open-access papers (continued):
Sharing a sentence is not in itself a finding about the gene and the disease.
melanoma (continued). "Previous publications have demonstrated a limited therapeutic efficacy of CD47 blockade in mice bearing the B16F10 melanoma tumor model." (PMID 38414061, 2024). "Significantly, two distinct clusters were formed based on the CD47 mRNA levels, high and low, which corresponded to the malignant melanoma patients cluster (high) and the normal skin cluster (low)." (PMID 39742254, 2024). "In conclusion, our data demonstrates that the promoter region required for efficient CD47 transcriptional activation in melanoma lies between -120 to +50bp relative to the TSS." (PMID 39742254, 2024). "B16F10 melanoma cells, known for PD-L1 and CD47 overexpression, were used for checkpoint block assay." (PMID 39588148, 2024). "Using serial DNA deletion analysis in combination with bioluminescence reporter systems, we determine that the minimum promoter region required for CD47 transcriptional activation in melanoma lies between -120 to +50bp relative to the TSS." (PMID 39742254, 2024). "The modulation of the CD47/SIRPα axis and phagocytosis by HDAC6is was investigated using murine and human melanoma cell lines and macrophages." (PMID 38414061, 2024). "The blockade of CD47 by our nanovesicles significantly enhanced the phagocytosis of melanoma cells by macrophages, facilitating the release and presentation of tumor-associated antigens and thereby promoting the maturation of dendritic cells." (PMID 39588148, 2024). "To understand molecular mechanisms of augmented CD47 mRNA expression in malignant melanoma, we investigated the dynamics of chromatin re-modeling at CD47 promoter using ATAC-Seq." (PMID 39742254, 2024). "As shown in this study, HDAC6 inhibition enhances phagocytosis of SM1 melanoma cells, an event regulated by the CD47/SIRPα axis." (PMID 38414061, 2024). "To further explore clinical significance of our findings, we investigated CD47 mRNA levels among 422 melanoma subjects in comparison to 123 normal skin subjects using TCGA TARGET GTEx dataset." (PMID 39742254, 2024). "This supports that anti-CD47 alone is insufficient to decrease tumor burden in melanoma-bearing mice and generate long-lasting antitumor immunity." (PMID 38414061, 2024). "In B16F10–CSCs bearing mice melanoma model, tumor hypoxia relief combined with synergetic inhibition of the CD47-SIRPα signaling pathway presented a robust effect in eradicating CSCs and inhibiting tumor growth." (PMID 38699238, 2024). "Next, to determine NRF-1 regulation of CD47 promoter, we performed Chromatin Immunoprecipitation (ChIP) assays on malignant patient-derived melanoma cells, as well as, adult normal melanocytes and HepG2 cells." (PMID 39742254, 2024). "The primary cilium also regulates cancer pathogenesis, and correlations between IFT57 mRNA and survival paralleled those for CD47 in thyroid and lung carcinomas, melanoma, and glioma." (PMID 39201643, 2024). "Our results demonstrate that peak signals for H3K4Me3 DNA modification at the CD47 promoter region are significantly stronger in malignant melanomas in comparison to normal melanocytes." (PMID 39742254, 2024). "Altogether, our results suggest that HDAC6 plays a role in regulating CD47 expression in melanoma cells and that HDAC6i can prevent IFNγ-driven upregulation of CD47." (PMID 38414061, 2024). "We also observed that the systemic administration of HDAC6i enhanced the in vivo antitumor activity of anti-CD47 blockade in melanoma by modulating macrophage and natural killer cells in the tumor microenvironment." (PMID 38414061, 2024). "The efficacy of immunotherapy against melanoma and colorectal cancer was enhanced by the simultaneous blocking of CD47 and PD-L1 using bispecific antibodies, which activated both innate and adaptive immune responses." (PMID 38532108, 2024). "Overall, our results show that NextA improves the antitumor efficacy of anti-CD47 in mouse melanoma models." (PMID 38414061, 2024).
melanoma (continued). "Inhibition of CXCR2 in G-MDSCs augments the efficacy of CD47 blockade in promoting melanoma tumor cell clearance." (PMID 38720108, 2024). "Here, we explore the role of the CD47-SIRPα interactions on myeloid function in a B16.F10 melanoma model." (PMID 38577107, 2024). "In order to evaluate endogenous NRF-1 activity at the CD47 promoter, we generated melanoma cell lines to stably express all versions of Luc reporters using previously published lentiviral transduction protocols." (PMID 39742254, 2024). "In summary, these findings indicate that CD47 transcriptional regulation by NRF-1 is determined by the proximal promoter region in melanoma cells." (PMID 39742254, 2024). "Lastly, we evaluated the antitumor properties of the combination of NextA and anti-SIRPα and NextA and anti-CD47 in vivo using the SM1 melanoma mouse model." (PMID 38414061, 2024). "This difference in binding affinity can be attributed to the presence of only CD47 on RBCs versus the co-expression of PD-L1 and CD47 on melanoma cells." (PMID 39588148, 2024). "The direct binding of CD47 to Gi proteins, coupled with its interaction with integrin ανβ3 in melanoma cells, highlights a potential mechanism by which CD47 regulates Gi signaling to promote cell migration." (PMID 39039207, 2024). "Preclinical studies using melanoma models demonstrated that combining anti-CD47 with anti-PD-L1 or antibodies targeting tumor-specific antigens provides more robust antitumor responses." (PMID 38414061, 2024). "After performing multiple qRT-PCR assays, our results demonstrate that all metastatic melanomas expressed 10-15 folds (depending on the isoform) elevation in CD47 mRNA as compared to normal melanocytes or HepG2 cells." (PMID 39742254, 2024). "We report here the experimental treatment of murine melanoma B16F10 tumors using a genetically engineered MyxV armed with CD47 and IFN-γ." (PMID 37835397, 2023). "Among them, we found Sparc, Cd47, Plec, Anxa1, Anxa 3, and Anxa 5, genes strongly involved in the metastatic processes of melanoma." (PMID 37898636, 2023). "The efficacy of MyxV_CD47/IFN-γ in B16F10 mouse melanoma syngeneic mouse models resulted in strong tumor regression and prolonged mouse survival." (PMID 37835397, 2023). "Analysis of mRNA expression data for melanomas in The Cancer Genome Atlas identified a significant coexpression of MYCN with CD47 and known regulators of CD8 T cell function." (PMID 36768931, 2023). "Based on their strong positive correlations with CD47 mRNA expression in the TCGA melanoma data, we selected MCL1, CD40LG, TNF, and TIGIT to examine their regulation by CD47 signaling in human Jurkat T lymphoblast cells." (PMID 36768931, 2023). "CD47-α4β1 interactions stimulated adhesion in melanoma, lymphoma, and T cells, and promoted migration in B-cell leukemia models." (PMID 37958404, 2023). "Consistent with these in vitro data, CD47 mRNA expression in TCGA melanomas had highly significant positive correlations with MCL1, CD40LG, TIGIT, and TNF mRNA expression." (PMID 36768931, 2023). "In contrast to the association of high CD47 and TIGIT with increased survival in melanoma, it is notable that the opposite was recently reported for lung squamous cell carcinoma." (PMID 36768931, 2023). "In melanoma models, CD47 expression was induced by IFNγ, although the exact mechanism remains to be elucidated." (PMID 37958404, 2023). "The increased growth of B16 melanomas in cd47−/− mice relative to the growth of the same tumors in WT mice is associated with impaired CD8 T cell and natural killer cell functions in the tumor microenvironment." (PMID 36768931, 2023). "Initially, CD47 was co-immunoprecipitated with heterotrimeric Gi proteins in membranes isolated from platelets, melanoma, and ovarian cancer cells, which was reversible by the potent inhibitor of receptor–Gi protein binding, pertussis toxin." (PMID 37958404, 2023).
melanoma (continued). "The cross-regulation we demonstrate between CD47 and other immune checkpoints we identified in melanomas supports further therapeutic trials combining CD47 blockades with ICIs targeting PD-1 and TIGIT." (PMID 36768931, 2023). "We therefore tested the effect of CD47 in CD8+ T cell in responding to implanted syngeneic melanoma in a mouse model." (PMID 36105746, 2022). "Similar to the B16F10 melanoma model, PQ/PB-Gel significantly down-regulated the expression of CD47 on the surface of 4T1 tumor cells." (PMID 35832081, 2022). "Immunohistochemically, CD47 has been investigated in bone marrow samples of patients with acute myeloid leukemia, melanoma, and ovarian cancer, but to the best of our knowledge, this is the first study of the role of CD47 in CUC." (PMID 36611344, 2022). "Correspondingly, chronic LCMV Cl13 infection as well as implantation of syngeneic B16 melanoma significantly elevated viral titer and also tumor growth, respectively, in Cd47−/− mice." (PMID 36105746, 2022). "Lung tumor nodules of syngeneic B16F10 melanoma cells with CD47 deletion show opsonization drives macrophage phagocytosis of B16F10s, consistent with growth versus phagocytosis calculus for exponential suppression of cancer." (PMID 35454837, 2022). "A siRNA targeting CD47 on tumor cells was systematically delivered by HA-coated lipid NPs into melanoma cancer cells, resulting in CD47 knockdown, which facilitated phagocytosis and led to the inhibition of melanoma growth and metastasis." (PMID 35189921, 2022). "In another report, aberrant N-glycosylation of the adhesion receptor SHPS-1 (also known as SIRPα1) has been related to the resistance of B16F10 melanoma cells to CD47-mediated negative regulation of motility." (PMID 34440905, 2021). "Sensitivity of B16 melanomas in immune-competent mice to ablation by tumor irradiation was enhanced when either Thbs1 or Cd47 were disrupted in the tumor microenvironment." (PMID 33925464, 2021). "Melanoma-bearing cd47−/− mice exhibited decreased splenic NK cell numbers, with impaired effector protein expression and elevated exhaustion markers." (PMID 33925464, 2021). "IHC analysis showed that all 3 human cell lines of glioblastoma, melanoma, and head and neck squamous cell carcinoma had reduced CD47 expression immediately after NTP treatment compared to controls." (PMID 33540720, 2021). "Cell lines MC38 (mouse colon cancer), B16 (mouse melanoma) and U87 (human glioblastoma) exposed to 800 nM BoxA also reduced surface CD47 after 24 or 48 h (Fig EV4A)." (PMID 33956406, 2021). "Extending these findings to the role of CD47 in cancer, we examined the NK cells in syngeneic B16 melanomas growing in WT versus cd47−/− mice." (PMID 33925464, 2021). "In this respect, CD47 antagonists and anti-PD-L1 reportedly elicit sustained anti-tumour effects and enhanced survival compared to anti-CD47 therapy alone in murine models of melanoma." (PMID 34944851, 2021). "Increased surface expression of DAMPs calreticulin (CRT), HSP70 and HSP90 was also detected in a panel of melanoma tumoursphere lines, and CD47, the inhibitory signal for phagocytosis by immune cells, was increased in three of the six lines tested." (PMID 34359633, 2021). "Disruption of TSP-1:CD47 interaction under TAX2 treatment indeed promotes accumulation of infiltrating CD3+ T cells within s.c. implanted melanoma tumors." (PMID 34638503, 2021). "Melanoma patients with tumors bearing CD47 overexpression were found to have worse overall survival rates and higher rates of distant metastasis." (PMID 34944850, 2021). "Consistent with this, oncogenic activation of ERK signal induces CD47 expression by NRF-1-mediated CD47 gene transcription in melanoma cells leading to inhibition of phagocytosis." (PMID 34512146, 2021). "Our in vitro and in vivo studies suggest that FUS directly prevented the CD47 counteraction of CRT expression in melanoma cells, significantly improving therapeutic regression of tumors." (PMID 32206098, 2020).
melanoma (continued). "A significantly superior tumor regression for CFUS relative to CRT-NP treated cells (n=5) was noted in the mice over 4-week, suggesting that CFUS directly prevented the CD47 counteraction of CRT expression in melanoma cells to improve the therapeutic response." (PMID 32206098, 2020). "Our work provides a systematic evaluation of melanoma cell phagocytosis by examining the effects of CD47 blockade on melanoma cells derived from human, mouse, and dog cells." (PMID 31205227, 2020). "We confirmed that human (M14) and canine (TLM1) melanoma cell lines expressed CD47 at levels comparable to human (Raji) and canine (CLBL1) lymphoma cells." (PMID 31205227, 2020). "In contrast to melanoma cells, both cell types exhibited a substantial increase in phagocytosis (31.2 ± 2.6% and 25.8 ± 2.1%, respectively) in response to CD47 blockade." (PMID 31205227, 2020). "To evaluate the ability of CD47 blockade to enhance phagocytosis of mouse melanoma cells in vitro, we incubated CFSE-labelled B16 cells with activated mouse J774 macrophages in the presence or absence of CV1-hIgG4." (PMID 31205227, 2020). "Previous studies have produced contradictory results regarding the efficacy of CD47 blockade in the treatment of melanoma." (PMID 31205227, 2020). "Interferencing CD47/SIRPα axis using anti-CD47 antibodies has been effective in inhibiting the growth of certain solid tumors including melanoma, lung cancer and leiomyosarcoma." (PMID 32824974, 2020). "We observed no defect in lymphoma cell phagocytosis or interference with CD47 blockade due to the melanoma cell supernatant." (PMID 31205227, 2020). "We began to evaluate the role of CD47 in melanoma cell phagocytosis by measuring CD47 expression on mouse B16 melanoma cells." (PMID 31205227, 2020). "We also assessed the potential to enhance antitumor effects of vaccination with anti-CD47 Ab-coated irradiated tumor cells in mice challenged with two different sublines of murine melanoma, B16F0 and B16F10." (PMID 31996683, 2020). "While we observed small increases in M14 and TLM1 melanoma cell phagocytosis in response to CD47 blockade, the overall percent phagocytosis of these cells (3.7 ± 1.0% and 12.4 ± 2.0%, respectively) remained low as compared to lymphoma cells." (PMID 31205227, 2020). "CD47 overexpression also correlates with poor prognosis in head and neck squamous cell carcinoma, melanoma, and osteosarcoma." (PMID 31921125, 2019). "We discovered that 33% of mice vaccinated with CD47−/− melanoma cells remained tumor-free at the end of 90 days post tumor challenge." (PMID 31882679, 2019). "We developed CD47−/− mouse melanoma B16F10 cell lines through CRISPR/Cas9 gene editing and inactivated them using gamma irradiation for vaccination." (PMID 31882679, 2019). "To understand the impact of this interplay between BNIP3-hypoxia-CD47 on the phagocytic clearance of melanoma cells by macrophages, we performed in vitro phagocytosis experiments." (PMID 29707136, 2018). "Treatment with BRAF/MEK inhibitors upregulated CD47 in cultured melanoma cells and fresh melanoma isolates." (PMID 29050218, 2017). "To further understand the effect of BRAF/MEK inhibition on the interaction between melanoma cells and the immune system, we have examined the potential effect of BRAF/MEK inhibitors on the expression of CD47 in melanoma cells." (PMID 29050218, 2017). "Paradoxically, treatment of melanoma cells or fresh melanoma isolates with BRAF/MEK inhibitors resulted in upregulation of CD47." (PMID 29050218, 2017). "The increase in CD47 expression was mediated by ERK signalling, as it was associated with rebound activation of ERK and co-knockdown of ERK1/2 by siRNA diminished upregulation of CD47 in melanoma cells after exposure to BRAF/MEK inhibitors." (PMID 29050218, 2017). "Our results showing that knockdown of ERK markedly inhibited the constitutive expression of CD47 indicate that its expression in melanoma cells is closely related to oncogenic activation of ERK." (PMID 29050218, 2017).
melanoma (continued). "Decreased expression of CD47 eventually led to growth inhibition of melanoma tumors and suppressed lung metastasis in a B16F10 murine melanoma tumor model." (PMID 28220118, 2017). "CFSE-labelled melanoma cells were added along with a blocking antibody against CD47 or the isotype control to cultures of human peripheral blood mononuclear cells (PBMC)-derived macrophages labelled with the red fluorescence dye PKH26." (PMID 29050218, 2017). "Regardless, our results have clearly demonstrated the important role of reactivation of ERK in CD47 upregulation in melanoma cells by BRAF/MEK inhibitors." (PMID 29050218, 2017). "Disruption of TSP-1:CD47 interaction under TAX2 treatment indeed promotes accumulation of infiltrating CD3+ T cells within melanoma tumors implanted in WT mice, especially around vascular structures and next to necrotic areas (data not shown)." (PMID 28794454, 2017). "This would argue against the role of the BRAF/MEK/ERK pathway in promoting CD47 expression in melanoma cells." (PMID 29050218, 2017). "We tested the potential effect of BRAF inhibitors on the expression of CD47 in melanoma cells by treating Mel-CV and MM200 cells (BRAFV600E) with the BRAF inhibitor vemurafenib for various periods." (PMID 29050218, 2017). "Irrespectively, these results demonstrate that high levels of CD47 are obliged for protection against macrophage phagocytosis of melanoma cells that express increased levels of CRT on the surface after exposure to BRAF/MEK inhibitors." (PMID 29050218, 2017). "In support, melanoma cells from post-treatment primary cultures with increased CD47 expression were more prone to macrophage phagocytosis than the corresponding pre-treatment cells upon CD47 blockade." (PMID 29050218, 2017). "We next examined the effect of the increased CD47 expression on macrophage phagocytosis of melanoma cells resistant to vemurafenib." (PMID 29050218, 2017). "Taken together, these results demonstrate that NRF-1 is responsible for BRAF/MEK-mediated regulation of CD47 expression in melanoma cells." (PMID 29050218, 2017). "As the only “don’t eat me” signal-generating protein on the target cell surface identified so far, CD47 expression is elevated on the surface of many types of cancer cells including melanoma cells." (PMID 29050218, 2017). "Here we report that oncogenic activation of ERK plays an important role in transcriptional activation of CD47 through nuclear respiratory factor 1 (NRF-1) in melanoma cells." (PMID 29050218, 2017). "Recent studies have shown that Cdc42 is activated downstream of CD47 and regulates melanoma cell migration." (PMID 27411490, 2016). "It has been shown that CD47 is overexpressed in human melanoma and its depletion using CD47 siRNA significantly inhibited melanoma growth and metastasis." (PMID 27839516, 2016). "Consistent with our data, CD47 was found to be elevated in clinical melanoma samples and delivery of siRNA targeting CD47 was recently reported to effectively inhibit melanoma tumor growth and lung metastasis." (PMID 26046793, 2015). "In the context of syngeneic melanoma allografts, morpholino suppression of CD47 expression induced only a modest decrease of tumor growth." (PMID 26578962, 2015). "Metastatic melanoma secreted TSP1 or blocking of CD47 attenuated the induction of TREGs by melanoma while induced TREGs were able to actively suppress the immune response." (PMID 22481923, 2012). "Another Ig-domain containing protein, CD47, has been shown to bind to αv-integrin and is present in early adhesion complexes at the leading edge of spreading melanoma and human vascular endothelial (HUVEC) cells." (PMID 15471548, 2004). "Therefore, it is likely that the observed increase in CD47 expression following NDV infection of melanoma, pancreatic, and ovarian cancers was mediated by NF-κB activation." (PMID 41322194, 2025). "Additionally, many cancer cells, including melanoma, overexpress CD47 on their surface, a “don’t eat me” signal." (PMID 40082557, 2025).